IL1B (interleukin 1 beta)
Diseases named in the same sentence as IL1B in open-access papers (continued):
Sharing a sentence is not in itself a finding about the gene and the disease.
depression (continued). "We aimed to evaluate serum tumor necrosis factor‐α (TNF‐α), interleukin‐1 beta (IL‐1β), interleukin‐6 (IL‐6), interleukin‐17 (IL‐17) levels, and their correlations with anxiety/depression in NSCLC survivors." (PMID 34697903, 2022). "Data consistently demonstrates that a subset of patients with depression show elevated levels of inflammatory biomarkers including Interleukin-6 (IL-6), Interleukin-1Beta (IL-1β), Tumour Necrosis Factor-alpha (TNF- α) and CRP." (PMID 35146459, 2022). "At present, many studies have confirmed that the levels of inflammatory factors such as IL-1β and IL-6 in the serum of patients with depression are dramatically increased." (PMID 35148670, 2022). "BA has showed potential therapeutic effect for depression by reducing the levels of proinflammatory factor IL-1β possibly through regulation of SIRT1-NF-κB pathway in BV-2 microglia." (PMID 36408278, 2022). "In conclusion, proinflammatory IL-1β and TNF-α showed to be more negatively correlated with white matter FA of the brain in outpatients with depression, particularly for IL-1β in the corpus callosum." (PMID 36261698, 2022). "It is believed that even psychosocial factors and bitter events of life, first cause an increase in pro-inflammatory biomarkers such as IL-1β, IL-6 and hs-CRP which is then followed by depression." (PMID 36368945, 2022). "Research showed in rats that depression can lead to increased secretion of IL-1B and TNFα and reduced tear secretion." (PMID 35332110, 2022). "It has been reported that patients suffering from depression present elevated serum levels of pro-inflammatory cytokines including interleukins, e.g., IL-1β, IL-6, and tumor necrosis factor-alpha (TNF-α)." (PMID 35740286, 2022). "Pro-inflammatory cytokine (IL-1β, TNF-α, IL-6) release has also been linked to depression-like behaviours and cognitive defects in mice." (PMID 34709564, 2022). "To validate that our model was successful and verify the relationship between central and peripheral cytokines and depression, we measured the mRNA expression and protein level of pro-inflammatory cytokines, including IL-6, IL-1β and TNF-α." (PMID 36357867, 2022). "In a clinical study on elderly patients with refractory depression, serum levels of IL-1β and TNF-α were decreased after rTMS treatment." (PMID 35392634, 2022). "It was reported that the mean concentration levels of IL-1β increased as depression became more severe." (PMID 35326343, 2022). "Overgrowth of endogenous or exogenous Escherichia leads to altered gut microbiota and disrupts gut immune homeostasis, leading to gut inflammation, depression, and cognitive impairment by inducing IL-1β and corticosterone production." (PMID 36620654, 2022). "For instance, a recent cumulative meta-analysis reported that interleukin-6 (IL-6), IL-1β and C-reactive protein (CRP) are associated with depression." (PMID 35496273, 2022). "Studies have shown that depression is related to the expression of a variety of molecules, including IL-6, IL-2, IL-1β, TNF-α, and C-reactive protein (CRP)." (PMID 36010610, 2022). "In conclusion, common inflammatory cytokines including TNF-α, IL-1β, and IL-17 were related to cognition impairment, anxiety, and depression in AIS patients in this study." (PMID 35239774, 2022). "Inflammatory signals are thought to play an important role in the development of depression and anxiety disorder, e.g., the cytokines IL-1β, IL-6, and TNFα." (PMID 35456304, 2022). "More recent studies have indicated that in the hippocampus EGCG provides relief from depression by downregulating IL-1β and upregulating BDNF in a mouse model." (PMID 36499295, 2022). "In the present study, we discovered that high TNF-α and IL-6 were correlated with cognition impairment occurrence; high TNF-α, IL-1β, and IL-17 were correlated with anxiety or depression occurrence in AIS patients." (PMID 35239774, 2022).
depression (continued). "In conclusion, common inflammatory cytokines including TNF-α, IL-1β, and IL-17 were related to cognition impairment, anxiety, or depression in AIS patients." (PMID 35239774, 2022). "A rat model of EAP complicated with depression was established and confirmed by increases in IL-1β, IL-6, and TNF-α as well as the occurrence of depressive‐like behaviors." (PMID 36250064, 2022). "Here, we demonstrated that the AGE-RAGE signaling pathway was involved in CORT-induced depression and promoted the secretion of proinflammatory cytokines (IL-1β and TNFα)." (PMID 35626632, 2022). "In the prefrontal cortex of a rat model of depression, interleukin (IL)-1β, IL-6, tumor necrosis factor-α (TNF-α), microglial activation, and NF-κB signaling are upregulated." (PMID 35496318, 2022). "SD stress has also been reported to induce depression by promoting the expression of proinflammatory cytokine genes, such as IL-1β and TNF-α, which are well-known stress markers." (PMID 36014820, 2022). "When PTSD co-occurred with depression, the concentration levels of IL-1β were observed to increase even more significantly." (PMID 35326343, 2022). "Both animal and human experimental studies suggested that IL-1β is a key mediator in the pathogenesis of depression." (PMID 35335195, 2022). "CSF concentrations of markers such as TNF-α and IL-1β are also correlated with depression severity, and exogenous induction of inflammation can produce some core features of depression." (PMID 35618889, 2022). "With the development of the cytokine theory of depression, it has been well documented that pro-inflammatory cytokines, including IL-1β, IFN, and TNF can reduce the bioavailability of neurotransmitters such as serotonin (5-HT)." (PMID 36232376, 2022). "It is similar to the results found in this study that the levels of IL-1β and IL-6 protein in the hippocampus of rats with depression increased." (PMID 35148670, 2022). "This has been supported by meta-analyses showing high levels of the same proinflammatory cytokines like RA (IL6, IL1β, and TNFα) in the peripheral blood of patients with depression compared with controls." (PMID 36422176, 2022). "IL-6 and IL-1β levels have been reported to be positively correlated with depression scores in postpartum women." (PMID 35721155, 2022). "The study assessed the concentration of IL-1β, IL-4, IL-8 and IL-10 in depression alone and with PTSD." (PMID 35326343, 2022). "Various studies demonstrate that, e.g., schizophrenia, depression, suicidal ideation and post-traumatic stress disorder are characterized with increased levels of inflammatory markers, particularly IL-1β, IL-2R, IL-6, IL-17A, TNF-α and CRP." (PMID 35682824, 2022). "It is noteworthy that IL-1β, IL-6, and IL-10 are the most frequently reported cytokines in depression and affective disorders." (PMID 36387880, 2022). "Depression-like symptoms can be alleviated by increasing the expression of Nrf2/HO-1 and decreasing the expression of IL-1β, IL-6, and TNF-α in the microglial cells." (PMID 35634375, 2022). "In the SEM, inflammatory markers (i.e., NLR, IL-1β as observed variables) and mental health (i.e., insomnia, depression, and anxiety as observed variables) were set as latent variables." (PMID 36210450, 2022). "As a key inflammation switch, P2X7 receptor participates in the development of depression by influencing the release of IL-1β." (PMID 35496273, 2022). "NAC also exerts an anti-inflammatory role by decreasing various cytokines in the brain, especially IL-6, TNF-α and IL-1β, which are involved in the inflammatory mechanisms of depression." (PMID 36291336, 2022). "It was shown that the IL-1β concentration correlated negatively with the wholebrain FA in the group with depression." (PMID 36261698, 2022). "Chronic uncontrolled stress was a major cause of depression, which leaded to the activation of caspase-1 by the NLRP3 inflammasome, followed by production of inflammatory cytokine such as IL-18 and IL-1β." (PMID 35281471, 2022).
depression (continued). "In the current study, we enrolled 217 NSCLC survivors to evaluate levels of TNF‐α, IL‐1β, IL‐6, and IL‐17 and their correlations with anxiety and depression." (PMID 34697903, 2022). "Astrocyte-specific reductions in Men1 levels enhance NF-κB activation and IL-1β production, leading to the development of depression in mice, and these effects can be rescued by an NF-κB inhibitor." (PMID 36052143, 2022). "Clinical studies have shown that inflammatory cytokines in the central nervous system are significantly elevated, such as IL-1β and IL-6, in patients with depression." (PMID 35069768, 2022). "Lymphocytes of patients with depression activate the production of IL-1b, IL-6, and TNF, and such inflammatory pathways are known to cause neuronal damage through oxidative and nitrosative stress." (PMID 35773440, 2022). "In this case, increased serum levels of IL-1β, IFN-α2, and IFN-γ are associated with MDD and this fact further adds a clinical link between GD and depression-like behavior." (PMID 35456041, 2022). "In general, antidepressant medications tend to reduce the levels of pro-inflammatory factors, such as TNF-α, IL-1β, and IL-6, found in many patients with depressive disorders." (PMID 35252227, 2022). "The knock down of IL-1β in the hippocampus alleviates lipopolysaccharide (LPS)-induced depression-like behaviors in mice." (PMID 34051074, 2021). "In people with MS with comorbid fatigue and/or depression, there are reported increased serum and CSF concentrations of the pro-inflammatory cytokines, such as interleukins (IL-1a, IL-1b, IL-2, IL-6), TNF-α and IFN-γ." (PMID 35242093, 2021). "Dahl found that serum IL-1β in patients with depression is significantly higher than that in healthy control group." (PMID 34479552, 2021). "LPS can increase the level of IL-1β and IL-6 in prefrontal cortex and lead to depression-like behavior in rats." (PMID 34079622, 2021). "The P2Y12 receptor in microglia induces interleukin-1β (IL-1β) expression, which is a key mediator of depression in the brain." (PMID 34930362, 2021). "A 2 year South Korean longitudinal study presented various correlations between five proinflammatory cytokine levels (TNF-α, IL-1α, IL-1β, IL-6, and IL-8) and late-life depression (LLD) from cross-sectional and prospective perspectives." (PMID 34299040, 2021). "The IL-1β plasma level has been reported to be increased in the postictal period in patients with MTLE and associated with depression in these patients." (PMID 34421794, 2021). "Following this, increased TNF-α and IL-1β were released into brain, inducing neuroinflammation and finally depression-like behaviors." (PMID 34827513, 2021). "P2Y12 shRNA and EA significantly downregulated the expression of P2Y12, weakened the activation of microglia, and then inhibited IL-1β expression in the mPFC, thus relieving visceral pain and depression-like behaviors in IBD mice." (PMID 34930362, 2021). "Heightened interleukin (IL)-1β and IL-18 signaling has been determined to propagate resistance to selective serotonin reuptake inhibitors (SSRIs) in certain entities of depression." (PMID 34443594, 2021). "The course of depression is often associated with changes in pro-inflammatory substances such as NLRP3 and IL-1β (Alcocer-Gómez, 2014)." (PMID 34526897, 2021). "Employment of the forced swimming test in a mice depression model, all the animals exhibited enhancement of IL-1β processing and release, which was mitigated by antidepressant administration." (PMID 34443594, 2021). "Chronic unpredictable mild stress can induce depression in mice and increase serum cytokines such as IL-1β, IL6, and TNFα." (PMID 34082798, 2021). "It is well established that patients with depression and anxiety have higher plasma levels of C-reactive protein and proinflammatory cytokines (e.g., TNFa, IL-1a, IL-1b, IL-4, IL-5, IL-6, IL-12, and interferon)." (PMID 33802143, 2021).
depression (continued). "The most commonly involved inflammatory markers observed in the pathogenesis of both depression and Psoriasis are IL-6, IL-17, IL-13, IL-23, IL-10, IL-1β, and type A cytokines (TNF-α, IL-2, INF-γ) through Th1 and Th17 lymphocytes mediated processes." (PMID 34183985, 2021). "The control of inflammation by α7 nAChR has been linked to depression, as knock-out mice for α7 nAChR were observed to develop a depression-like phenotype and exhibit high levels of TNF-α and IL-1β." (PMID 34948222, 2021). "In conjunction with measures of pregnancy-specific anxiety and depression, serum biomarkers (IL-2, IL-6, IL-10, IL1-B, TNF-α, CRH, CRP, and cortisol) were analyzed for each trimester throughout pregnancy." (PMID 34360332, 2021). "Depression risk is bidirectionally associated with the levels of pro-inflammatory cytokines such as tumor necrosis factor-α (TNF-α), interleukin-1β (IL-1β), and IL-6." (PMID 34475376, 2021). "In the present study, many anti-depressant targets of EMO against depression were associated with the inflammatory response such as IL6, TNF, IL10, CRP, IL1B, CTLA4, ALB and IL2." (PMID 34051074, 2021). "Since CHOP and related UPR are able to induce the expression of IL1β and can cause inflammatory reactions, a connection between the increased UPR and the inflammatory reaction in depression seems possible." (PMID 33580474, 2021). "Some brain penetrable P2X7R antagonists such as BBG and A-438079 have exhibited antidepressant effects in chronic unpredictable mild stress (CUMS) mice model of depression by inhibiting the activation of P2X7/NLRP3/IL-1β pathway." (PMID 33889073, 2021). "In agreement with our data, overproduction of Caspase-1 in the hippocampus or intracerebroventricular administration of IL-1β induces depression- and anxiety-like behaviors in mice." (PMID 34258564, 2021). "In rats, the administration of IL-1β led to adult hippocampal neurogenesis reduction, which also promotes depression-like behaviors." (PMID 34827513, 2021). "The levels of pro-inflammatory cytokines (IL-1β and IL-6) are increased in some brain regions of patients with depression." (PMID 34051074, 2021). "Wohleb and colleagues found that treatment with propranolol reduced the expression of inflammatory markers on microglia and macrophages, as well as reduced microglial IL-1β mRNA expression in their mouse model of stress-induced anxiety and depression." (PMID 34563566, 2021). "Peripheric inflammation activation such as the increased levels of IL‐1β, IL‐6, and interferon‐γ are found in depressive patients or animal model of depression." (PMID 34492157, 2021). "Severity of depression significantly decreased after treatment, and the decrease in IL-1β:IL1ra ratio significantly influenced antidepressant response." (PMID 34539454, 2021). "For example, vagotomy consistently blocks depression-like behaviors induced by peripheral injection of LPS and IL-1β–induced behavioral depression." (PMID 33591956, 2021). "Ketamine administration decreased the levels of IL-6, TNF-α, and IL-1β and suppressed the activation of NF-κB in depressed mice, suggesting pro-inflammatory inhibition plays an important role in depression treatment." (PMID 34772918, 2021). "Procaspase-1 is subsequently converted to activated caspase-1, which further promotes the secretion of IL-1β, thereby generating a corresponding inflammatory response and promoting the pathogenesis of depression." (PMID 33505499, 2021). "EA significantly downregulated P2Y12 expression, weakened the activation of microglia, and then inhibited IL-1β expression in the mPFC, thus relieving visceral pain and depression in IBD mice." (PMID 34930362, 2021). "P2X7 receptor activation by ATP followed by NLRP3 induced IL-1β release that results in neuroinflammation are major contributors of neuropsychiatric disorders, especially depression." (PMID 33889073, 2021).
depression (continued). "The NPC patients with depression showed significantly higher levels of IL-1β and IL-2 relative to healthy comparisons, while patients without depression only had higher IL-2 than healthy subjects (p<0.05 after FDR correction)." (PMID 34900691, 2021). "In patients with depression, specific brain changes and evaluated IL-1β were identified, and the IL-1β interacted with right precentral gyrus to significantly affect the depressive symptoms." (PMID 34900691, 2021). "EA inhibited the expression of P2Y12 and IL-1β in the mPFC and weakened the activation of microglia, thus relieving visceral pain and depression in IBD mice." (PMID 34930362, 2021). "Two meta-analyses showed reliably higher levels of inflammatory markers in depression, namely IL-1β, IL-6, C-reactive protein (CRP), and TNF-α." (PMID 34975571, 2021). "We found that LPS administration induced significant elevation of TNF-α, IL-1β, and IL-6 inflammatory cytokines levels, while these have been reported to contribute to the pathogenesis of depression." (PMID 34207497, 2021). "Among them, IL-1β is the key molecule mediating the depression-like behaviors induced by acute and chronic stress." (PMID 34930362, 2021). "It is known that pro-inflammatory cytokines are sufficient to induce symptoms of depression in patients and that IL1β as well as IL6 play a prominent role in this mechanism." (PMID 33580474, 2021). "Especially with regard to CSF WBC the results are surprising since CSF inflammatory markers such as TNF-α and IL-1β measured in the cerebrospinal fluid of treatment-naive MS patients correlate with depression scores." (PMID 34764926, 2021). "In animal models of depression, IL-6 (and/or IL-1β appears to be instrumental for the development of chronic stress and depression-like behaviors." (PMID 34367160, 2021). "Evidence suggests that some inflammatory mediators, such as tumor necrosis factor alpha (TNF-α) and interleukin-1beta (IL-1β), are involved in the development of depressive disorders." (PMID 33564342, 2021). "Pro-inflammatory cytokines, including IL-1β, IL-6, IL-12, TNF-α, and IFN-γ, are thought to be associated with depressive disorders." (PMID 34576215, 2021). "It was recently shown that NLRP3 inflammasomes participate in stress-induced depression by regulating IL-1β production in serum as well as in the hippocampus." (PMID 32377306, 2020). "A known proinflammatory cytokine, IL-1β accelerates the development of insulin resistance, stress, depression, and CNS dysfunction." (PMID 32166013, 2020). "When subjected to adverse stimuli, P2X7 ion channels are activated to induce the release of NLRP3-induced proinflammatory factors, such as IL-1β, leading to neuroinflammation of the CNS and increasing incidence of depression." (PMID 32166013, 2020). "It has been reported that the stress-sensitive NLRP3 inflammasome, which is activated in blood cells from depression patients, plays an important role in priming of microglia, such as induced the activation and amplified expression of IL-1β in the CNS." (PMID 32922291, 2020). "In combined models of pain and depression, increases in the cytokines IL-1β and IL-6 in the amygdala have also been noted." (PMID 32849076, 2020). "We described the important link between IDO-1 upregulation, the IL-1β signaling pathway, serotonergic (hypoactive) and glutamatergic (hyperactive) transmission, and depression." (PMID 32842609, 2020). "The α7 nAChR positive allosteric modulator (PAM), PNU120596, prevented LPS-induced depression-like behaviors in mice, hindered activation of microglia and astrocytes, and inhibited the upregulation of IL-1β and TNF-α in the hippocampus and prefrontal cortex." (PMID 33100903, 2020). "The present study aimed to examine the impact of CSA on inflammatory biomarkers (IL-6 and IL-1β) in adults with depression and the mediating role of trust." (PMID 32413063, 2020).